IL10 (interleukin 10)
Diseases named in the same sentence as IL10 in open-access papers (continued):
Sharing a sentence is not in itself a finding about the gene and the disease.
colitis (continued). "Interestingly, NZ-HO increased the production of IL-10, decreased inflammatory cell infiltration, and decreased expression of IL-6 and IL-1α in the colonic tissue of murine colitis models." (PMID 28179904, 2017). "We suggest that BF prevents DSS-colitis via the TLR2/IL-10 signal pathway." (PMID 28683149, 2017). "IL-10 modulates the severity of colitis, and IL-10−/− mice spontaneously develop disease." (PMID 26998523, 2016). "We also examined whether IL-10 KO Treg-of-B cells retained the capability to suppress T cell proliferation and prevent colitis, both in vivo and in vitro." (PMID 27581189, 2016). "In vitro cultued, OVA-specific Tr1 cells prevent colitis through the IL-10 production." (PMID 27581189, 2016). "Moreover, IL-10 control of Foxp3+ Treg is necessary to maintain immune homeostasis in a colitis transfer model." (PMID 27027442, 2016). "Importantly, treatment of IL-10-/- mice with neomycin-metronidazole before and after the establishment of colitis ameliorated colitis parameter and diminished adherent bacterial levels indicating protective effects." (PMID 27853192, 2016). "Now we find that CD11b attenuates DSS-induced colitis by promoting TLR-triggered IL-10 expression via Src-Akt pathway, indicating the critical role of CD11b and its downstream signal Src in maintaining immune homeostasis and controlling TLR-induced innate inflammatory response." (PMID 27188220, 2016). "IL-10 appears to be essential for maintaining Foxp3+ Treg differentiation in colitis." (PMID 27022966, 2016). "Mice infected with Hymenolepis diminuta and treated with the adult worm extract or treated with IL-4/IL-13–differentiated M2 macrophages have significantly reduced pathology in experimentally induced colitis; this protective effect is abrogated when IL-10 or macrophages are depleted." (PMID 27101372, 2016). "Moreover, in IL-10 KO mice with colitis, it was demonstrated that the VSL#3 probiotic upregulates Alk-SMase activity, suggesting its potential as anti-inflammatory agent." (PMID 26880864, 2016). "The major source of ameliorating IL-10 in colitis is from macrophages." (PMID 26998523, 2016). "Our results are consistent with other investigations that showed T. spiralis excretory-secretory antigen-stimulated dendritic cells alleviated experimental autoimmune encephalomyelitis or DSS-induced colitis through inducing Treg that increased the secretion of IL-4, IL-10 and TGF-β." (PMID 27809931, 2016). "The findings demonstrate that (i) Ab-mediated IL-10 neutralization leads to progressive colitis with a reduction in Foxp3+ regulatory T cells and increased numbers of CD8+CD44+ memory T cells as well as activated CD4+CD69+ and CD8+CD69+ T cells in uninfected mice." (PMID 27611574, 2016). "Administration of rSjcystatin significantly reduced inflammatory parameters and ameliorated the severity of the TNBS-induced colitis through decreasing IFNγ in three organs and lifting the level of IL-4, IL-13, IL-10, and TGF-β in the colon tissues, with uptrending Tregs in the MLN and LPMC." (PMID 26728323, 2016). "It was then demonstrated that Clostridium butyricum when used as a probiotic, could induce IL-10 production from macrophages in colonic mucosa, which resulted in suppression of acute colitis in mice." (PMID 27350830, 2016). "While Lcn2 KO mice did not develop spontaneous colitis, a rapid onset and development of colitis was observed in Lcn2/IL-10 DKO mice soon after the weaning period compared to IL-10 KO mice, suggesting that the innate immune responses were disrupted in the colonic tissues of Lcn2/IL-10 DKO mice." (PMID 27734904, 2016). "Tollip regulates the severity of DSS-induced and spontaneous colitis in IL-10 KO mice." (PMID 27741296, 2016). "Furthermore, the fecal concentration of Lcn2 in IL-10 KO mice remarkably increased within a time interval of 12 weeks of colitis induction in the IL-10 KO mice and was significantly positively correlated with the degree of histological inflammation." (PMID 27734904, 2016).
colitis (continued). "Recurrent infections, intermittent folliculitis, early onset colitis, and perianal disease leading to fistula formation and colostomy requirement together with positive family history in this patient suggested probable IL-10/IL-10R defects." (PMID 27699073, 2016). "Following our preliminary observation that CD11b-deficient mice are more susceptible to DSS-induced colitis, in this study, we uncovered the polarizing role and the underlying mechanisms of CD11b in promoting TLR-triggered IL-10 production in macrophages and DCs." (PMID 27188220, 2016). "In this study, CD4+CD25+Foxp3− cells and the production of IL-10 significantly decreased in IL-21RKO mice with DSS-induced colitis, which may contribute to aggravate the development of colitis." (PMID 27545302, 2016). "In addition, the fecal concentration of Lcn2 increased in IL-10 KO mice with the development of colitis, thus supporting the notion that Lcn2 is secreted from colonic epithelial cells in response to inflammatory signals." (PMID 27734904, 2016). "In oxazolone-induced, Th2-mediated colitis, VD enhanced both Th2- and Treg-mediated inflammation, and the up-regulated Treg cells could secrete anti-inflammatory cytokines, such as IL-10 and TGF-β1, that could partially counteract Th2 inflammatory response." (PMID 27620138, 2016). "In IL-10-/- experimental colitis models, IL-10-expressing B cells alleviate colitis." (PMID 27515534, 2016). "Importantly, Src inhibitor dasatinib aggravated DSS-induced colitis by decreasing IL-10 while increasing TNF-α in vivo." (PMID 27188220, 2016). "Therefore, CD11b promotes IL-10 production and protects mice from colitis through Src-Akt signal cascade." (PMID 27188220, 2016). "Additionally, the immunomodulatory potential of L. lactis strains carrying the IL-10-coding vector pValac::IL-10 has been successfully shown in colitis induced by both TNBS and dextran sulphate sodium (DSS)." (PMID 27576902, 2016). "Therefore, in the present study, we investigated the role of Lcn2/NGAL in intestinal inflammation using a spontaneous mouse colitis model, interleukin-10 knock out (IL-10 KO) mice." (PMID 27734904, 2016). "Moreover, disruption of STAT3 in bone marrow cells resulted in a CD-like phenotype in mice prior to death, and suppression of experimental colitis by CX3C chemokine receptor 1-bearing myeloid cells was dependent on STAT3 activation by IL-10." (PMID 26938566, 2016). "IL-10 is known to be a potent anti-inflammatory cytokine in colitis and may exert a tumor suppressive role in CRC." (PMID 26799669, 2016). "Genetic ablation of IL-10 results in both colitis and jejunitis in these animals." (PMID 26881175, 2016). "Lcn2 expression in the colonic tissues of IL-10 KO mice increased with the development of colitis." (PMID 27734904, 2016). "We speculated that IL-10, which is highly secreted by Treg-of-B cells, might be responsible for the protective effects of Treg-of-B cells in colitis." (PMID 27581189, 2016). "It has been shown that Lactobacillus (L.) reuteri could be used to prevent colitis in IL-10−/− mice by increasing the number of lactobacilli in the GIT." (PMID 26064086, 2015). "The IL-10-producing Mos inhibited the experimental colitis in mice." (PMID 25588622, 2015). "In this innate immune model of colitis, Tpl2−/− mice experienced milder colitis compared to wild type mice with reduced production of inflammatory cytokines IL-1α, IL-1β, IL-6, and IL-17, as well as reduced production of the anti-inflammatory cytokine IL-10." (PMID 25781948, 2015). "LPMCs isolated from OPN/IL-10 DKO mice expressed higher levels of TNF-α and IL-12p40 than those from IL-10 KO mice at 4 weeks of age, suggesting that intestinal macrophages are highly activated in OPN/IL-10 DKO mice at an early stage of colitis compared to IL-10 KO mice." (PMID 26274807, 2015).
colitis (continued). "Thus, an intriguing notion is that OPN secreted from colonic epithelia prevents the development of colitis in IL-10 KO mice by affecting enteric bacteria, including Clostridium subcluster XIVa." (PMID 26274807, 2015). "Analogous to the inflammation-promoting activity of AIEC mediated by adhesion to intestinal mucosal surfaces, we demonstrate that proximity of bacteria to the intestinal epithelium is a contributing prerequisite for E. faecalis-induced colitis in monoassociated IL-10-/- mice." (PMID 26067254, 2015). "Opportunistic pathogens shown to exert detrimental effects in susceptible mouse models include: Helicobacter hepaticus and Bilophila wadsworthia that are capable of triggering colitis in IL-10-/- mice in combination with specific microbiota composition or dietary exposure." (PMID 26067254, 2015). "Similarly, mice lacking FoxP3+ Tregs or lacking the ability to suppress via Treg-derived cytokines such as IL-10, IL-35, and TGFβ develop severe colitis." (PMID 25944983, 2015). "Interestingly, the authors showed that daily oral administration of L. lactis IL-10 in mice resulted in ~50% reduction in dextran sulfate sodium (DSS)-induced colitis." (PMID 25889561, 2015). "Moreover, intravenously or rectally administered NFκB p65 antisense oligonucleotides ameliorate 2,4,6-trinitrobenzene sulfonic acid (TNBS)-induced colitis and colitis in IL10-/- mice." (PMID 26241646, 2015). "To test the suppressive function of the IL-10-expressing Mos, we created a colitis mouse model." (PMID 25588622, 2015). "Those mice that were Cyp27b1 (−/−) showed decreased IL-10 in the proximal colon and Toll-like receptors 2 and 4 in the distal colon as well as decreased levels of circulating 1,25(OH)2VitD, thus implicating vitamin D affecting colitis in DSS‐treated mice." (PMID 27417766, 2015). "This therapeutic function is mediated through TNFR2 and IL-10, as rPGRN lost its effect in TNFR2 deficient colitis model and its therapeutic effect could be blocked by neutralizing the IL-10 antibody." (PMID 26408020, 2015). "Although the larger size of the rat has several advantages over the smaller mouse, in general more investigations into the pathophysiology of intestinal disease in people employ mice as the primary rodent model, as underscored by the utility of IL-10 knockout mice used to study colitis." (PMID 26561503, 2015). "Moreover, the type-1 cystatin derived from the liver fluke Clonorchis sinensis (C. sinensis) significantly reduced intestinal inflammation by recruiting IL-10-secreting macrophages in a dextran-sodium-sulfate (DSS)-induced colitis mice model." (PMID 25879741, 2015). "The IL-10-expressing Mos show an immune suppressive function on experimental colitis in mice." (PMID 25588622, 2015). "OPN/IL-10 DKO mice had an accelerated onset of colitis compared to IL-10 KO mice." (PMID 26274807, 2015). "Treg cells play an important role in intestinal homeostasis and suppress colitis in part via IL-10." (PMID 26200014, 2015). "The involvement of IL-10 in intestinal tolerance was confirmed in a model of experimental colitis." (PMID 25759839, 2015). "Due to the association between IBD/CRC and a higher colonization with pks positive bacteria, Arthur and co-workers have used germ-free IL-10 to knock out mice (IL-10−/−, model for IBD) treated with the colon-specific carcinogen azoxymethane (AOM) as a model for colitis-associated CRC." (PMID 26270677, 2015). "Thus, specific IL-10 deletion of Foxp3+ Tregs results in spontaneous colitis, highlighting the fact that IL-10 produced by Tregs is instrumental in maintaining tolerance particularly at intestinal tissues." (PMID 24711809, 2014). "However, NOD2 was also reported to promote the secretion of the anti-inflammatory cytokine IL-10 as well as proliferation of regulatory T cells during murine colitis." (PMID 25068517, 2014). "Likewise, IL10−/− and iIL10−/− offspring showed similar histological grades of colitis (3.0 ± 1.1 and 2.7 ± 1.1)." (PMID 24849654, 2014).
colitis (continued). "Follow-up studies are needed to determine whether this vector system would be effective in treating other models of murine colitis such as the IL-10 knock out model of murine colitis." (PMID 24712338, 2014). "Moreover, our results also showed significantly increased transcriptional levels of IL-4 and IL-10 in the colon tissues of ERC-treated colitis mice compared to untreated colitis mice." (PMID 25475342, 2014). "These IL-10 gene containing particles have shown to successfully reduce the levels of inflammatory cytokines as well as disease activity scores in the TNBS-induced model of colitis." (PMID 25106058, 2014). "Autocrine production of IL-10 limits VDR KO CD8+ T cell- induced colitis." (PMID 24502291, 2014). "We demonstrated further that BregIL-33 isolated from these mice could suppress immune effector cell expansion and functions and, upon adoptive transfer, effectively blocked the development of spontaneous colitis in IL-10−/− mice." (PMID 24491821, 2014). "The observation that IL-10 decreases the production of IL-17 by cells from CL and ML patients supports other studies that show that IL-10 can regulate IL-17 production in other inflammatory diseases such as colitis and chronic pulmonary Mycobacterium avium infection." (PMID 24485388, 2014). "Interestingly, whereas induction of colitis in IL-10−/− mice born under SPF conditions and in mice exposed to DSS is prevented by ciprofloxacin and metronidazole respectively, these antibiotics have minimal effect after the onset of colitis." (PMID 24616886, 2014). "Reasoning that administration of DNA beads might ameliorate inflammation in colitis conditions; we examined the effects of DNA beads in models of both acute (DSS-induced colitis) and chronic colitis (IL-10 KO mice that spontaneously developed colitis)." (PMID 25127031, 2014). "Therefore it seems that autocrine IL-10 production by CD8+ T cells prevents overt colitis induced by VDR KO CD8+ T cells." (PMID 24502291, 2014). "However, in the present study, IL-10-production by T-LPL was rather impaired in immune milk-fed mice after induction of colitis by DSS, excluding this possibility." (PMID 24686517, 2014). "In this study, we tested whether efficient local gene transfer can be accomplished using LV expressed murine IL-10 (mIL-10) in a murine colitis model." (PMID 24712338, 2014). "Moreover, BF protected against experimental colitis induced by TNBS or Helicobacter hepaticus via interleukin 10 (IL-10) inducing CD4+ and Foxp3+ regulatory T-cell development." (PMID 24971344, 2014). "However, adoptive transfer of Treg cells inhibits the development of gut inflammation in this colitis model, which depends on the ability of transferred cells to express IL-10." (PMID 24489792, 2014). "Similar to that shown in human patients with GC-C mutation, we show here that deletion of GC-C in mice results in rapidly developing, severe colitis in a spontaneous intestinal inflammation model (IL-10−/− mice) that closely resembles human inflammatory bowel disease (IBD)." (PMID 24244444, 2013). "While monoassociation with H. hepaticus has been reported to cause sporadic colitis in mono-associated Swiss Webster mice during very long-term infection, that does not normally hold true for the widely used Il10−/− mice." (PMID 23951007, 2013). "Recently, it was demonstrated that IL-10 produced by iTreg cells could replace nTreg cell-derived IL-10 in the cure of experimental colitis." (PMID 23801990, 2013). "In the IL-10−/− mouse, cytokine expression and inflammation depends upon the presence of microbiota; mice housed in germ free environments do not develop colitis and treatments aimed at modifying gut bacteria can both prevent and treat the colitis." (PMID 23638009, 2013). "Higher expression levels of IL-10 in the colon may be involved in the protection of CD69 KO mice from severe colitis." (PMID 23785429, 2013).
colitis (continued). "In our current study, the mechanisms responsible for IL-4 or IL-10 anti-colitis could be due to control of pro-inflammatory cytokine production and immune cells accumulation in gut tissues." (PMID 24314293, 2013). "Experiments using the Il10−/− H. hepaticus-induced colitis model are usually conducted in the presence of a normal mouse microbiota or SPF microbiota; the exact composition of which remains mostly unknown." (PMID 23951007, 2013). "Finally, Clostridium species induce the development of IL-10-producing regulatory T cells in the murine colon, which protect against chemically-induced colitis and suppress systemic immunoglobulin E responses." (PMID 23750260, 2013). "IL-10−/− mice had colitis that was mild by 6 weeks of age in CCHMC specific pathogen free vivarium." (PMID 24244444, 2013). "Also species belonging to Bacteroidetes can promote tolerance in the gut, as Bacteroides fragilis was shown to induce Treg and IL-10 production and to prevent and cure experimental colitis in mice." (PMID 24244309, 2013). "Interestingly, the IL-10-/- B cell mice developed a "colitis-like" disease with symptoms including rectal pro-lapse with some bleeding, sticky stool consistency, increased intestinal-gas (seen by dissection) and loss of body weight (data not shown)." (PMID 22315945, 2012). "NHE3 is the most important sodium absorptive transporter and responsible for the majority of electroneutral salt absorption in the intestine, and is the only functionally recognized sodium absorptive transporter in the proximal-mid colon, the area most affected by IL-10−/− colitis." (PMID 22848392, 2012). "In this study, mice deficient in both TNF and IL-10 (T/I mice) were found to spontaneously develop severe colitis soon after weaning, without the need for exogenous triggers." (PMID 22848611, 2012). "We have independently shown that commensal strains of Escherichia coli exert protective effects in the developing colon through the induction of the type I interferon IFNαA, and that the anti-inflammatory effects of IFNαA are dependent on IL-10 production in adult models of colitis." (PMID 23272193, 2012). "In this study, IL-10−/− mice were analyzed for immunological changes during colitis development." (PMID 22400037, 2012). "IL-10 is a regulatory cytokine that plays a major role in the homeostasis of the gut and this is illustrated by the fact that IL-10−/− mice develop spontaneous colitis." (PMID 22400037, 2012). "ADI-PEG treatment protects against colitis in 2 distinct phenotypic animal models, BALB/c wildtypes as well as IL-10 deficient mice, presumably due to the attenuation of inflammatory markers such as SAA, suppression of macrophage infiltration, and iNOS expression in colonic tissues." (PMID 22315509, 2012). "CO exposure at a concentration of 250 ppm for 7 days ameliorated colitis in IL-10−/− mice." (PMID 22943587, 2012). "We found that liver hepcidin expression was up-regulated in the piroxicam/IL-10 knockout colitis model and the Rag knockout/T cell transfer colitis model, while other investigators have demonstrated elevated hepcidin levels in the spontaneous ilietis of TNFΔARE mice." (PMID 22675442, 2012). "Importantly, IL10 is required to maintain immune homeostasis in the gut, where Treg-specific deletion of IL-10 leads to colitis in mice." (PMID 22973511, 2012). "Surprisingly, we determined an up-regulation of regulatory cytokine IL-10, which could be a result of a biological feedback aimed at dampening down the local inflammation, similar to chronic experimental colitis." (PMID 22629361, 2012). "However, IL-10 treatment in humans with colitis is disappointing due to low mucosal availability and proinflammatory effects at higher doses of IL-10." (PMID 21811497, 2012). "It is well documented that mice lacking IL-10 have a predisposition to immune-driven colitis and inflammation of the gut." (PMID 22315945, 2012).